LINC00459 (long independently transcribed non-coding RNA 459)
Gene: Long non-coding RNA gene on chromosome 13 (62,323,657 to 62,328,833, forward strand). Ensembl gene ENSG00000229307.
Diseases named in the same sentence as LINC00459 in open-access papers:
LINC00459 is named in the same sentence as 3 diseases in open-access papers, as found by Europe PMC text mining. Sharing a sentence is not in itself a finding about the gene and the disease. The quoted sentences say what the papers report.
melanoma (2 papers, 2019 to 2022). A malignant, usually aggressive tumor composed of atypical, neoplastic melanocytes. "Additionally, the rescue experiment suggested that the suppression of cell proliferation and invasion that caused by overexpression of LINC00459 could be reversed by the transfection of miR-218 mimic in melanoma cells to a great extent." (PMID 31844121, 2019). "Multivariate analyses indicated the LINC00459 expression level in melanoma could be an independent risk factor for the OS (HR: 1.752, 95% CI: 1.021–3.219, P = 0.036), while lower expression level of the LINC00459 could also lead to less PFS (HR: 2.405, 95% CI: 1.210–4.782, P = 0.012)." (PMID 31844121, 2019). "In contrast, FENDRR, PINT, and LINC00459 are weakly expressed in melanoma and execute antioncogenic roles by inhibiting malignant processes." (PMID 33674778, 2022). "LINC00459 which on chromosome 13q21.31 with 2 exons was significantly decreased in melanoma tissues according to the result of microarray profiling." (PMID 31844121, 2019). "We also discovered that the expression of LINC00459 in melanoma cell lines is also lower than that in normal melanophores." (PMID 31844121, 2019). "In this study, we found that the expression of LINC00459 in melanoma tissues is much lower than that in pigmented nevus tissues." (PMID 31844121, 2019). "The RT-qPCR indicated that the LINC00459 expression in melanoma cell lines was significantly down-regulated comparing to that in human melanocytes cells (HEM) (P < 0.05)." (PMID 31844121, 2019). "The FISH demonstrated the LINC00459 mainly existed in the cytoplasm of the melanoma cell lines." (PMID 31844121, 2019). "Here we did not perform loss-of-function assays as the expression of LINC00459 in melanoma was relatively low." (PMID 31844121, 2019). "What’s more, the RT-qPCR demonstrated that the increasing LINC00459 level could inhibit the expression of miR-218 in melanoma cells." (PMID 31844121, 2019). "The results demonstrated decreased LINC00459 in melanoma cell lines and tissues." (PMID 31844121, 2019). "To better understand the mechanism that LINC00459 impacts progression of melanoma, we further identified and validated LINC00459/miR-218/DKK3 pathway that regulated the proliferation and invasion ability of melanoma cells." (PMID 31844121, 2019). "LINC00459 may act as an endogenous competitive RNA to sponge miR-218 and thus moderate the effector DKK3 to regulate the proliferation and migration of melanoma." (PMID 31844121, 2019). "In conclusion, our research results indicate that the LINC00459/miR-218/DKK3 pathway may be a novel therapeutic target and biomarker in melanoma." (PMID 31844121, 2019). "In melanoma cell lines A375 and UACC903, the exogenous expression of LINC00459 is increased, the cell viability is reduced, the proportion of cells in the G2/M stage is decreased, the apoptosis rate is increased, and the invasion and migration capacities of cells are weakened." (PMID 31844121, 2019).
nevus (1 paper, 2019). Nevus (or naevus, plural nevi or naevi, from nævus, Latin for "birthmark") is the medical term for sharply circumscribed[1] and chronic lesions of the skin or mucosa. "According to the ISH, the expression level of the LINC00459 was decreased in tumor tissues comparing with the pigmented nevus tissues." (PMID 31844121, 2019).
tumor (2 papers, 2019 to 2021). "Cancer susceptibility candidate 2 (CASC2), LINC00961, LINC00459 and maternally expressed gene 3 (MEG3) have been described as tumor-suppressor lncRNAs in melanoma." (PMID 33503876, 2021). "Its expression levels are lower in tumor tissues compared to the pigmented nevus tissues and, surprisingly, the median overall survival in the LINC00459 low-expression group is significantly lower than in the high-expression group." (PMID 33503876, 2021). "Smaller tumor volume and lower tumor weight were observed in the mice with overexpressed LINC00459." (PMID 31844121, 2019).